SPATS2 (spermatogenesis associated serine rich 2)
Synonyms: SCR59; SPATA10; Nbla00526; FLJ13117; P59SCR
Tractability: PROTAC: ubiquitination databases record sites on it; its protein half-life has been measured.
Gene: Protein-coding gene on chromosome 12 (49,366,240 to 49,528,438, forward strand). Ensembl gene ENSG00000123352.
Subcellular location: Cytoplasm
Subcellular location (Human Protein Atlas): Cytosol
Gene Ontology:
Molecular function: RNA binding
Cellular component: cytosol; cytoplasm
Genetic constraint (gnomAD): Loss-of-function variants: 35 observed, 60.68 expected, observed/expected ratio (o/e) 0.58, 90% interval 0.44 to 0.76. The upper end of that interval is the gene's LOEUF score, 0.76, which puts it in group 3 of 6, group 1 being the genes least tolerant of losing a copy. Missense variants: 580 observed, 684.93 expected, observed/expected ratio (o/e) 0.85, 90% interval 0.79 to 0.91. Synonymous variants: 205 observed, 241.69 expected, observed/expected ratio (o/e) 0.85, 90% interval 0.76 to 0.95.
Homologues: Orthologues: chimpanzee SPATS2 (99% identical), macaque SPATS2 (96% identical), dog SPATS2 (91% identical), pig SPATS2 (89% identical), guinea pig SPATS2 (86% identical), mouse Spats2 (84% identical), rat Spats2 (82% identical), rabbit SPATS2 (79% identical), tropical clawed frog spats2 (59% identical), Caenorhabditis elegans Y71F9AL.9 (14% identical). Paralogues in human: SPATS2L (39% identical).